CENPV (centromere protein V)
Description:
Required for distribution of pericentromeric heterochromatin in interphase nuclei and for centromere formation and organization, chromosome alignment and cytokinesis.
Synonyms: CENP-V; PRR6; p30; 3110013H01Rik
Tractability: PROTAC: ubiquitination databases record sites on it; its protein half-life has been measured.
Gene: Protein-coding gene on chromosome 17 (16,342,534 to 16,353,656, reverse strand). Ensembl gene ENSG00000166582.
Subcellular location: Chromosome, centromere, kinetochore; Nucleus; Cytoplasm, cytoskeleton, spindle
Subcellular location (Human Protein Atlas): Nucleoplasm; Cytokinetic bridge; Cytosol; Midbody; Nuclear membrane; Nucleoli
Gene Ontology:
Molecular function: protein binding; carbon-sulfur lyase activity; microtubule binding
Biological process: ameboidal-type cell migration; pericentric heterochromatin formation; positive regulation of cytokinesis; regulation of chromosome organization
Cellular component: kinetochore; microtubule cytoskeleton; nuclear membrane; nucleolus; nucleoplasm; nucleus; spindle midzone; chromosome, centromeric region; microtubule organizing center; spindle; spindle microtubule
Genetic constraint (gnomAD): Loss-of-function variants: 10 observed, 17.81 expected, observed/expected ratio (o/e) 0.56, 90% interval 0.34 to 0.95. The synonymous counts are far from expectation, so gnomAD's model fits this gene poorly and the ratio says little. Missense variants: 310 observed, 278.67 expected, observed/expected ratio (o/e) 1.11, 90% interval 1.01 to 1.22. Synonymous variants: 156 observed, 107.94 expected, observed/expected ratio (o/e) 1.45, 90% interval 1.27 to 1.65.
Homologues: Orthologues: chimpanzee CENPV (100% identical), macaque CENPV (96% identical), dog CENPV (80% identical), mouse Cenpv (73% identical), rat Cenpv (71% identical), pig CENPV (64% identical), rabbit CENPV (59% identical), guinea pig CENPV (55% identical), tropical clawed frog cenpv (52% identical), zebrafish cenpv (37% identical), Caenorhabditis elegans F25B4.8 (23% identical). Paralogues in human: CENPVL3 (51% identical), CENPVL1 (51% identical), CENPVL2 (51% identical).
Diseases named in the same sentence as CENPV in open-access papers:
CENPV is named in the same sentence as 9 diseases in open-access papers, as found by Europe PMC text mining. Sharing a sentence is not in itself a finding about the gene and the disease. The quoted sentences say what the papers report.
dysplasia (1 paper, 2021). A usually neoplastic transformation of the cell, associated with altered architectural tissue patterns. "CENPV was underexpressed in two dysplasia datasets with fold change of -2.075 and -2.392." (PMID 34457090, 2021).
leukemia (1 paper, 2022). A malignant (clonal) hematologic disorder, involving hematopoietic stem cells and characterized by the presence of primitive or atypical myeloid or lymphoid cells in the bone marrow and the blood. "The observed effects of the combination on KMT2A-r leukemia cell survival were associated with downregulated expression of genes involved in proliferation and cell cycle progression including MKI67, CCNB1, CENPV, CDK4 and cMYC in infant KMT2A-r leukemia cells PER-485, PER-703 and PER-494." (PMID 35677155, 2022).
cancer (2 papers, 2013 to 2025). A tumor composed of atypical neoplastic, often pleomorphic cells that invade other tissues. "CENPV encodes Centromere Protein V, a vital component involved in the process of mitosis and exhibiting significant upregulation in several cancer types." (PMID 40313868, 2025).
CENPV also shares sentences with these, for which no sentence is quoted: basal cell carcinoma (1 paper); cognitive decline (1); COVID-19 (1); frontotemporal dementia (1); skin tumors (1); tumor (1).